NCBP2 (nuclear cap binding protein subunit 2)
Description:
Component of the cap-binding complex (CBC), which binds co-transcriptionally to the 5' cap of pre-mRNAs and is involved in various processes such as pre-mRNA splicing, translation regulation, nonsense-mediated mRNA decay, RNA-mediated gene silencing (RNAi) by microRNAs (miRNAs) and mRNA export. The CBC complex is involved in mRNA export from the nucleus via its interaction with ALYREF/THOC4/ALY, leading to the recruitment of the mRNA export machinery to the 5' end of mRNA and to mRNA export in a 5' to 3' direction through the nuclear pore. The CBC complex is also involved in mediating U snRNA and intronless mRNAs export from the nucleus. The CBC complex is essential for a pioneer round of mRNA translation, before steady state translation when the CBC complex is replaced by cytoplasmic cap-binding protein eIF4E. The pioneer round of mRNA translation mediated by the CBC complex plays a central role in nonsense-mediated mRNA decay (NMD), NMD only taking place in mRNAs bound to the CBC complex, but not on eIF4E-bound mRNAs. The CBC complex enhances NMD in mRNAs containing at least one exon-junction complex (EJC) via its interaction with UPF1, promoting the interaction between UPF1 and UPF2. The CBC complex is also involved in 'failsafe' NMD, which is independent of the EJC complex, while it does not participate in Staufen-mediated mRNA decay (SMD). During cell proliferation, the CBC complex is also involved in microRNAs (miRNAs) biogenesis via its interaction with SRRT/ARS2, thereby being required for miRNA-mediated RNA interference. The CBC complex also acts as a negative regulator of PARN, thereby acting as an inhibitor of mRNA deadenylation. In the CBC complex, NCBP2/CBP20 recognizes and binds capped RNAs (m7GpppG-capped RNA) but requires NCBP1/CBP80 to stabilize the movement of its N-terminal loop and lock the CBC into a high affinity cap-binding state with the cap structure. The conventional cap-binding complex with NCBP2 binds both small nuclear RNA (snRNA) and messenger (mRNA) and is involved in their export from the nucleus.
Synonyms: CBP20; NIP1; PIG55; Cbc2
Tractability: Small molecule: a drug acting on it is in phase 2 or 3 trials; a structure with a bound ligand is known; it has a binding pocket of medium quality. PROTAC: ubiquitination databases record sites on it; its protein half-life has been measured.
Gene: Protein-coding gene on chromosome 3 (196,935,402 to 196,942,594, reverse strand). Ensembl gene ENSG00000114503.
Subcellular location: Nucleus; Cytoplasm
Subcellular location (Human Protein Atlas): Nucleoplasm; Basal body; Cytosol
Pathways (Reactome):
Metabolism of RNA: Nonsense Mediated Decay (NMD) enhanced by the Exon Junction Complex (EJC); Nonsense Mediated Decay (NMD) independent of the Exon Junction Complex (EJC); Nuclear RNA decay; Processing of Capped Intron-Containing Pre-mRNA; Processing of Intronless Pre-mRNAs; SLBP Dependent Processing of Replication-Dependent Histone Pre-mRNAs; SLBP independent Processing of Histone Pre-mRNAs; Transport of Mature mRNA Derived from an Intronless Transcript; Transport of Mature mRNA derived from an Intron-Containing Transcript; Transport of the SLBP Dependant Mature mRNA; Transport of the SLBP independent Mature mRNA; mRNA 3'-end processing; mRNA Capping; mRNA Polyadenylation; mRNA Splicing - Major Pathway; mRNA Splicing - Minor Pathway; snRNP Assembly
Disease: Abortive elongation of HIV-1 transcript in the absence of Tat; Dengue Virus-Host Interactions; Formation of HIV elongation complex in the absence of HIV Tat; Formation of HIV-1 elongation complex containing HIV-1 Tat; Formation of the HIV-1 Early Elongation Complex; Signaling by FGFR2 IIIa TM
Gene expression (Transcription): Formation of RNA Pol II elongation complex; Formation of the Early Elongation Complex; RNA Polymerase II Pre-transcription Events; RNA Polymerase II Transcription Termination; RNA polymerase II transcribes snRNA genes
Developmental Biology: Regulation of expression of SLITs and ROBOs
Signal Transduction: FGFR2 alternative splicing
Gene Ontology:
Molecular function: DNA binding; mRNA binding; protein binding; RNA 7-methylguanosine cap binding; RNA binding; snRNA binding; RNA cap binding; nucleic acid binding
Biological process: histone mRNA metabolic process; mRNA cis splicing, via spliceosome; mRNA export from nucleus; mRNA metabolic process; mRNA transcription by RNA polymerase II; nuclear-transcribed mRNA catabolic process, nonsense-mediated decay; positive regulation of mRNA 3'-end processing; regulation of translational initiation; alternative mRNA splicing, via spliceosome; cap-dependent translational initiation; miRNA-mediated post-transcriptional gene silencing; mRNA 3'-end processing; mRNA splicing, via spliceosome; positive regulation of RNA export from nucleus; positive regulation of transcription elongation by RNA polymerase II; primary miRNA processing; regulatory ncRNA-mediated post-transcriptional gene silencing; RNA splicing; snRNA export from nucleus
Cellular component: cytoplasm; cytosol; nuclear cap binding complex; nucleoplasm; nucleus; RNA cap binding complex
Genetic constraint (gnomAD): Loss-of-function variants: 8 observed, 21.74 expected, observed/expected ratio (o/e) 0.37, 90% interval 0.22 to 0.66. The upper end of that interval is the gene's LOEUF score, 0.66, which puts it in group 2 of 6, group 1 being the genes least tolerant of losing a copy. Missense variants: 127 observed, 216.84 expected, observed/expected ratio (o/e) 0.59, 90% interval 0.51 to 0.68. Synonymous variants: 92 observed, 80.56 expected, observed/expected ratio (o/e) 1.14, 90% interval 0.96 to 1.36.
Homologues: Orthologues: pig NCBP2 (100% identical), macaque NCBP2 (99% identical), guinea pig NCBP2 (98% identical), mouse Ncbp2 (98% identical), rat Ncbp2 (98% identical), chimpanzee NCBP2 (94% identical), tropical clawed frog ncbp2 (84% identical), zebrafish ncbp2 (80% identical), Drosophila melanogaster Cbp20 (70% identical), Caenorhabditis elegans ncbp-2 (60% identical). Paralogues in human: NCBP2L (65% identical).
Diseases named in the same sentence as NCBP2 in open-access papers:
NCBP2 is named in the same sentence as 37 diseases in open-access papers, as found by Europe PMC text mining. Sharing a sentence is not in itself a finding about the gene and the disease. The quoted sentences say what the papers report.
pancreatic cancer (7 papers, 2017 to 2025). "Knockdown of NCBP2 suppressed the growth of pancreatic cancer, while overexpression of NCBP2 promoted the growth of pancreatic cancer." (PMID 40448344, 2025). "Nuclear cap binding protein subunit 2 (NCBP2), an m7G‐binding protein, is upregulated in pancreatic cancer and is associated with poor prognosis." (PMID 40448344, 2025). "The orthotopic pancreatic tumor model was constructed by injecting control and NCBP2-knockdown Panc 05.04 cells into the pancreas of nude mice." (PMID 38001714, 2023). "A total of 8 immune genes (ITGA7, RBM14, DENND4B, LQK1, ZNF709, COL7A1, SP1, NCBP2) were identified as independent prognostic factors of pancreatic cancer, which were used to construct a clinical predictive model." (PMID 33546693, 2021). "NCBP2 exhibited significant upregulation in pancreatic cancer tissues compared with normal tissues." (PMID 40675967, 2025). "Subsequently, we evaluated the effect of NCBP2 on pancreatic tumor growth in-vivo." (PMID 38001714, 2023). "NCBP2 binds to m7G‐modified c‐JUN mRNA and enhances MEK/ERK signaling by upregulating c‐JUN translation, thereby promoting pancreatic cancer growth." (PMID 40448344, 2025). "Moreover, NCBP2 facilitates the translation of c-JUN, a protein that activates the MEK/ERK signaling pathway, thereby promoting the growth and proliferation of pancreatic cancer cells." (PMID 40124611, 2025). "However, NCBP2, RBM14, LQK1, and ZNF709 have not been reported to be related to pancreatic cancer." (PMID 33546693, 2021).
liver cancer (4 papers, 2021 to 2023). An epithelial or non-epithelial malignant neoplasm that arises from the liver. "However, further research is needed to establish diagnostic accuracy and treatment with NCBP2 in liver cancer." (PMID 36010268, 2022). "Among the genes associated with the prognosis of liver cancer, the genes associated with shorter survival period are AGO2, DCPS, IFIT5, LARP1, NCBP2, NUDT10, and NUDT16; the genes associated with longevity are EIF4E3, EIF4G3, METTL1, NCBP1, NSUN2, NUDT11, NUDT4, and WDR4." (PMID 36845384, 2023). "Moreover, in their study, the mRNA of NCBP2 in liver cancer tissues was also in significant upregulation (p < 0.0001) while in the comparison to normal tissues." (PMID 36118897, 2022). "The expression level of NCBP2 in liver cancer cell lines was analyzed using the CCLE online platform, and the result showed that the liver cancer cell lines with the highest expression of NCBP2 was from the HEP3B cell, and the lowest was from the JHH6 cell." (PMID 36010268, 2022). "Moreover, among of them, RFC4, ZWINT, UPF3B, NCBP2, ADA, SF3A3 and GTF2H1 are independent prognostic indicators of liver cancer." (PMID 33516217, 2021).
acute myeloid leukemia (3 papers, 2022 to 2025). Acute myeloid leukemia (AML) is a group of neoplasms arising from precursor cells committed to the myeloid cell-line differentiation. "The latest study revealed that NCBP2 was overexpressed in the high-risk group of acute myeloid leukemia (AML) and was negatively correlated with survival." (PMID 36010268, 2022). "For NCBP2 is one of the genes that is closely related to the prognosis of acute myeloid leukemia (AML), the risk score and nomogram results on pediatric AML research suggested that NCBP2 may be a risk factor for the malignant tumor." (PMID 36118897, 2022).
glioma (3 papers, 2022 to 2023). A benign or malignant brain and spinal cord tumor that arises from glial cells (astrocytes, oligodendrocytes, ependymal cells). "On the other hand, there were no considerable differences in the protein levels of EIF4E, EIF4E3, and NCBP2 between healthy brain tissues and lower-grade glioma tissues." (PMID 36998056, 2023). "Immunohistochemistry analysis showed that EIF4E, EIF4E3, and NCBP2 were increased in lower-grade glioma tissues, while lower-grade glioma did not cause a significant difference in EIF4E2 and NCBP1 proteins." (PMID 36998056, 2023). "In contrast, immunohistochemical analysis of 10 refractory epilepsy tissues and 10 lower-grade gliomas (WHO grade II-III) tissues showed that lower-grade gliomas did not significantly increase in EIF4E2 and NCBP1 protein expression, while EIF4E, EIF4E3, and NCBP2 were increased." (PMID 36998056, 2023).
hepatocellular carcinoma (3 papers, 2022 to 2025). A malignant tumor that arises from hepatocytes. "Moreover, the m7G-associated gene NCBP2 has been linked to hepatocellular carcinoma patient prognostic outcomes." (PMID 36482181, 2022). "NCBP2 was elevated in head and neck squamous cell carcinoma tissues, and overexpression of NCBP2 promotes hepatocellular carcinoma cells proliferation and migration." (PMID 40124611, 2025). "Recent studies also emphasize the significance of NCBP2 in cancer immunity in various cancers, such as hepatocellular carcinoma and head and neck squamous cell carcinoma." (PMID 40124611, 2025). "Overexpression of NCBP2 was enhanced, whereas blocking NCBP2 expression suppressed the migration of hepatoma cells." (PMID 35784919, 2022). "NCBP2 was also significantly overexpressed in hepatoma cells (HepG2 and HuH-7) compared to that in normal liver epithelial cells (THLE-3)." (PMID 35784919, 2022). "The biofunctions of NCBP2 in hepatocellular cancer (HC) cells were confirmed through qPCR, CCK8, and transwell assays." (PMID 35784919, 2022). "CCK8 assays revealed that overexpression of NCBP2 promoted the proliferation of hepatoma cells." (PMID 35784919, 2022).
lung carcinoma (3 papers, 2022 to 2023). "Bioinformatics analysis of The Cancer Genome Atlas (TCGA) dataset showed that NCBP1 and NCBP2 are highly expressed in lung cancer tissues and their expression levels are associated with poor prognosis." (PMID 35818360, 2022). "Overexpression of NCBP1 and NCBP2 are associated with lung cancer progression." (PMID 35818360, 2022). "NCBP1, a partner of NCBP2, promotes proliferation, migration, and wound healing of lung cancer cell lines." (PMID 35818360, 2022). "In a meta-analysis of the molecular mechanisms of miR-193a-5p, it was found that NCBP2 was one key miR-193a-5p target gene, both of its mRNA and protein expression were significantly upregulated in lung cancer." (PMID 36118897, 2022).
oral squamous cell carcinoma (3 papers, 2023 to 2025). "Moreover, several studies have indicated that NCBP2 promotes the proliferation, metastasis, and immune escape of oral squamous cell carcinoma and head and neck squamous cell carcinoma." (PMID 38001714, 2023).
ovarian carcinoma (3 papers, 2022 to 2023). A malignant neoplasm originating from the surface ovarian epithelium. "In screening out the biomarkers related to chemoresistance of ovarian carcinomas, NCBP2 was selected as a potential key gene through the protein-protein interaction network analysis." (PMID 36118897, 2022). "In ovarian carcinoma, NCBP2 has been reported as a key target gene." (PMID 35620469, 2022).
COVID-19 (2 papers, 2022). A disease caused by infection with severe acute respiratory syndrome coronavirus 2. "The expression levels of DBH-AS1, FLVCR1-DT, the antisense long non-coding RNA of FLVCR1 and NCBP2AS2-1, and the antisense long non-coding RNA of NCBP2 in COVID-19 patients in this study were deregulated, with a significant increase in both patient groups in comparison with controls." (PMID 36359290, 2022). "Furthermore, we observed that the major transcript of multiple genes switched to a different transcript (isoform switching) between COVID-19 patients and controls, such as IL2, IL34, SERPINE2, NCBP1, HRAS, PRPF6, NCBP2, and LUC7L2." (PMID 35421082, 2022).
melanoma (2 papers, 2022 to 2025). A malignant, usually aggressive tumor composed of atypical, neoplastic melanocytes. "Subsequent analysis demonstrated that elevated NCBP2 expression was linked to improved survival rates and response to anti-PD-L1 therapy in bladder cancer, whereas it was associated with poorer survival outcomes in melanoma." (PMID 40124611, 2025).
acute lymphoblastic leukemia (1 paper, 2022). Leukemia with an acute onset, characterized by the presence of lymphoblasts in the bone marrow and the peripheral blood. "For example, NCBP2 was upregulated in an acute lymphoblastic leukemia rearrangement child patient (r ALL) compared with non-r ALL patients." (PMID 36010268, 2022).
bladder cancer (1 paper, 2025). "In the urinary system tumors of the IMvigor210 cohort (bladder cancer), relationship between NCBP2 and the response to anti-PD-L1 treatment was analyzed." (PMID 40124611, 2025).
Epstein-Barr virus infection (1 paper, 2023). An infection that is caused by Epstein-Barr virus. "Specifically, SIRT6 was enriched in thermogenesis, while PSMD14 and PSMC6 were enriched in Epstein-Barr virus infection, and NCBP2 and PYM1 were enriched in nucleocytoplasmic transport." (PMID 37958518, 2023).
lung squamous cell carcinoma (1 paper, 2025). "IHC confirmed the aberrant expression of NCBP2 in lung squamous cell carcinoma (LUSC), pancreatic adenocarcinoma (PAAD), kidney renal papillary cell carcinoma (KIRP) and kidney renal clear cell carcinoma (KIRC)." (PMID 40124611, 2025).
non-small cell lung carcinoma (1 paper, 2021). A group of at least three distinct histological types of lung cancer, including non-small cell squamous cell carcinoma, adenocarcinoma, and large cell carcinoma. "Among of them, NCBP2 has the maximum weighting coefficient and has been reported to interfere with the drug sensitivity of platinum in non-small cell lung cancer." (PMID 33516217, 2021).
Sepsis (1 paper, 2021). Sepsis is defined as life-threatening organ dysfunction caused by a dysregulated host response to infection. "In particular, the qPCR analysis showed significant down-regulation of RPL11, RPS21, NCBP2, and MRRF during sepsis." (PMID 34594344, 2021). "The transcription levels of RPL11 (ribosomal protein L11), RPS21 (ribosomal protein S21), NCBP2 (nuclear cap binding protein subunit 2), and MRRF (mitochondrial ribosome recycling factor) were found to be significantly reduced in the sepsis group as compared to the control group (p‐value < 0.05)." (PMID 34594344, 2021).
squamous cell carcinoma (1 paper, 2023). A carcinoma arising from squamous epithelial cells. "Given the growing number of studies describing the prognostic value of TFRC in squamous cell carcinomas, we focused our attention on NCBP2 for further assessing effects on cancer aggressiveness." (PMID 36635327, 2023). "NCBP2 and TFRC proteins were primarily expressed in the nuclear and cytoplasmic compartments, respectively, and expression of both proteins was primarily restricted to squamous cell carcinoma cells in the tumour microenvironment." (PMID 36635327, 2023).